AHR (aryl hydrocarbon receptor)
Diseases named in the same sentence as AHR in open-access papers (continued):
Sharing a sentence is not in itself a finding about the gene and the disease.
Hypertension (continued). "The AHR pathway has been reported to interact with nitric oxide (NO), the renin–angiotensin system (RAS), and gut microbiota, which are crucial mechanisms underlying hypertension, to affect blood pressure (BP)." (PMID 32604820, 2020). "Since maternal AhR activation is related to programmed hypertension and kidney disease in adult offspring, AhR antagonists might be a potential reprogramming strategy to reverse programming processes and prevent adverse outcomes." (PMID 33218054, 2020). "As such, whether other AHR-activating microorganisms can serve as a reprogramming strategy to prevent hypertension of developmental origins deserves additional investigation." (PMID 32604820, 2020). "The AHR can activate distinct transcription factor pathways that contributes to hypertension." (PMID 32604820, 2020). "Additionally, AhR antagonist resveratrol has been reported to protect offspring against hypertension in several developmental hypertension models." (PMID 33218054, 2020). "An additional protective mechanism of tryptophan supplementation on programmed hypertension in this model may be related to mediation of the AHR signaling pathway." (PMID 32604820, 2020). "Resveratrol, an antioxidant and an AHR antagonist, may serve as a reprogramming strategy to prevent hypertension programmed by HF + BPA exposure." (PMID 31489946, 2019). "As such, whether other AHR antagonists can provide a therapeutic approach to prevent hypertension of developmental origins requires further study and clarification." (PMID 30127255, 2018). "Notably, that AHR pathway has been reported to interact with oxidative stress and the RAS, two central mechanisms underlying hypertension, to affect BP." (PMID 30127255, 2018). "Increasing evidence indicates that vascular α1D-adrenoceptor overexpression is another influential factor of hypertension in AhR−/− mice, and hypertension could be reversed by treatment with captopril." (PMID 29984241, 2018). "An additional protective mechanism of resveratrol on programmed hypertension in this two-hit model may be related to mediation of the AHR signaling pathway." (PMID 30127255, 2018). "Captopril could alleviate high blood pressure in AhR−/− mice, in part because of the reduction of Ang II." (PMID 29984241, 2018). "As for the AhR bioactivity data, further adjustment for a history of myocardial infarction, stroke, heart failure, diabetes and medication for hypertension, diabetes or hyperlipidaemia only had a marginal effect on the correlations between ATP concentration and TEQ or individual POPs." (PMID 28839207, 2017). "In an animal model, chronic exposure of TCDD was found to sustain AhR activation, leading to systemic hypertension and left ventricular hypertrophy, which might be mediated in part by increased superoxide." (PMID 26963719, 2016). "We hypothesized that an interplay between aryl hydrocarbon receptor (AhR) and cysteine-related thiolome at the kidney cortex underlies the mechanisms of (mal)adaptation to chronic intermittent hypoxia (CIH), promoting arterial hypertension (HTN)." (PMID 34573115, 2021). "Perinatal TCDD exposure caused hypertension in adult male offspring coinciding with reduced α-diversity, increased the Firmicutes to Bacteroidetes ratio, less abundant beneficial bacteria, impaired SCFA receptors’ expression, the activation of AHR signaling, and the aberrant activation of the RAS." (PMID 34578924, 2021). "Prior research suggests AHR target genes might be involved in TCDD-induced hypertension." (PMID 34578924, 2021). "Additionally, TCDD, an aryl hydrocarbon receptor (AHR) ligand, has been linked with hypertension." (PMID 32752013, 2020). "Therefore, it is possible that gene therapy targeting AhR signaling could be a potential candidate in the treatment of essential hypertension." (PMID 29984241, 2018).
Hypertension (continued). "RES was able to restore NO bioavailability, decrease oxidative stress, and inhibit AHR signaling, thereby preventing HF + BPA-induced hypertension in adult male offspring." (PMID 39449418, 2024). "We observed that high-dose RBE that protected offspring against hypertension coincided with decreased renal expression of ARNT and AHR downstream of the target gene CYP1A1." (PMID 36771404, 2023). "There are studies indicating that certain AhR agonists, such as indoxyl sulfate and hexachlorobenzene (HCB) induce hypertension and vascular dysfunctions in mice." (PMID 36757399, 2023). "A previous study showed that TCDD-induced hypertension coincided with TH17-induced renal inflammation, as well as AhR signaling activation." (PMID 35743061, 2022). "Another study showed that TCDD-induced programming hypertension is related to TH17-induced renal inflammation, the activation of AhR signaling, and alterations of gut microbiota compositions." (PMID 35453625, 2022). "Sustained aryl hydrocarbon receptor (AhR) activation by 2,3,7,8-TCDD exposure induces hypertension in adult male C57BL/6 mice." (PMID 36360663, 2022). "The effects of dioxins are mainly mediated by the aryl hydrocarbon receptor (AHR)—a ligand-activated transcription factor that contribute to the pathogenesis of CKD and hypertension." (PMID 34721300, 2021). "In another model of programmed hypertension, DMB therapy was reported to prevent adult offspring against hypertension coinciding with restoration of the balance of RAS and antagonization of AHR signaling." (PMID 34578924, 2021). "In view of the dysregulation of the RAS and AHR pathways involved in programmed hypertension, we next evaluated the components of RAS and AHR target genes in offspring kidneys." (PMID 34578924, 2021). "Our findings support interplay among tryptophan-metabolizing microbiome, AHR, NO, and the RAS in hypertension of developmental origins." (PMID 32604820, 2020). "There are several protective mechanisms by which maternal DMB therapy moderates hypertension programmed by combined HFR+TCDD exposure, such as increasing NO bioavailability, balancing the RAS, antagonizing AHR signaling, and restoring the gut microbiota." (PMID 32752013, 2020). "The interplay between AHR, nitric oxide (NO), the renin–angiotensin system (RAS), and gut microbiota is involved in the development of hypertension." (PMID 32604820, 2020). "Our study provides new insights into the protective roles of maternal tryptophan supplementation on hypertension programmed by maternal CKD through regulation of the gut microbiota compositions and AHR signaling pathways." (PMID 32604820, 2020). "As the nitric oxide (NO) and aryl hydrocarbon receptor (AHR) signaling pathways both contribute to the pathogenesis of hypertension, we evaluated whether resveratrol, an antioxidant and an AHR antagonist, can prevent hypertension programmed by a maternal BPA and HF diet." (PMID 31489946, 2019). "Several important mechanisms by which maternal resveratrol therapy protects offspring against combined TCDD and DEX exposure-induced programmed hypertension reduce oxidative stress, increase NO bioavailability, block the RAS, and antagonize AHR signaling." (PMID 30127255, 2018). "However, inhibition of ET-1 could not only lower mean arterial pressure and the levels of ET-1, but also reduce Ang II expression levels in AhR−/− mice with hypertension, indicating involvement of the regulation of the ET-1-Ang II axis in hypertension in AhR−/− mice induced by hypoxia." (PMID 29984241, 2018). "The CHD group exhibited significantly higher proportions of male sex, advanced age, smoking history, hypertension, T2DM, and antilipidemic drug use, along with elevated serum levels of ALT, GGT, HbA1c, Glu, Cr, AHR, LDL-c, AST, TG, and UA, compared with the control group (all P < 0.05)." (PMID 40809897, 2025).
Hypertension (continued). "Our objective in this study was first to determine whether TCDD exposure exacerbates HFR-induced hypertension via mediation of the gut microbiota-dependent TMA-TMAO metabolic pathway, AHR signaling, RAS, and the NO pathway." (PMID 32752013, 2020). "In the cardiovascular system, the absence of AhR can result in abnormal cardiac function, hypertension or hypotension, vascular dysfunction, and cardiovascular disease." (PMID 29984241, 2018). "Considering that the activation of the AHR/CYP1A1 axis can induce vasoconstriction, RBE suppressed renal ARNT/CYP1A1 expression might, at least in part, contribute to its beneficial actions against DEHP-primed hypertension." (PMID 36771404, 2023). "We examined whether perinatal resveratrol therapy prevents offspring hypertension programmed by maternal TCDD exposure and whether its beneficial effects are related to reshaping gut microbiota and antagonizing AHR-mediated T helper 17 (TH17) cells responses using a maternal TCDD exposure rat model." (PMID 34573025, 2021). "This intersection analysis showed that the final list of shared genes among hypertension, NAFLD, fibrosis and inflammation contained only four genes, including LEP, ADIPOQ, AHR and TGFB1, which could be regarded as important genes related to hypertension and NAFLD." (PMID 34096467, 2021). "Considering activation of the AHR/CYP1A1 axis induces vasoconstriction, resveratrol suppress renal CYP1A1 expression might, at least in part, contribute to its beneficial effects against TCDD-induced hypertension." (PMID 34573025, 2021). "On the other hand, maternal DMB therapy protects progeny against hypertension programmed by TCDD, which is related to alterations of gut microbiota composition, mediation of TMA-TMAO metabolic pathway, regulation of SCFA and their receptors, and restoration of the RAS and AHR signaling pathway." (PMID 34578924, 2021). "Thus, the beneficial effects of resveratrol on DEX + TCDD-induced hypertension include reduction of oxidative stress, restoration of nitric oxide (NO) bioavailability, blockade of the renin–angiotensin system (RAS), and antagonizing AHR signaling pathway." (PMID 30127255, 2018). "Taken together, these results suggest that the interplay between gut microbiota, AHR-mediated TH17 responses, and renal inflammation in the gut and kidneys may play an important role in the action of resveratrol against TCDD-induced programming of hypertension." (PMID 34573025, 2021). "Moreover, AHR signaling can modulate pro-inflammatory T helper 17 (TH17) axis and trigger inflammation, by which environmental chemicals may link to the development of hypertension and kidney disease." (PMID 34721300, 2021).
diabetes (50 papers, 2011 to 2025). "A previous study indicated that the activation of peroxisome proliferator-activated receptor alpha (PPARα) via interacting with the aryl hydrocarbon receptor is a potential biological mechanism of the association between PCBs and diabetes." (PMID 35578291, 2022). "AhR activation, although much less widely acknowledged, is also epidemiologically associated with diabetes." (PMID 21849270, 2011). "Several examples of AhR involvement in mechanisms underlying drug-induced diabetes were described." (PMID 41440753, 2025). "Environmental AhR ligands may disrupt glucose homeostasis and β-cell function through AhR activation in β-cells, potentially increasing diabetes susceptibility." (PMID 41440753, 2025). "An association between diabetes complications and AhR has been reported." (PMID 36418969, 2022). "Persistent organic pollutants (POPs) may cause diabetes, in part through aryl hydrocarbon receptor (AhR) binding." (PMID 33046063, 2020). "However, when TCDD treatment was stopped after 15 weeks, mice exhibited lower number of Tregs and decreased activation of AHR associated with development of diabetes over the next 8 months after treatment was terminated." (PMID 30574142, 2018). "The mechanisms by which long-term AhR activation causes diabetes are currently unknown." (PMID 21849270, 2011). "These investigations aim to shed light on the role of AhR in diabetes and enhance our understanding of its involvement in β-cell function." (PMID 39791758, 2025). "Since these environmental toxins depend on AhR to exert their toxic effects, AhR is likely to play a role in diabetes development, insulin resistance, and glucose homeostasis." (PMID 40408591, 2025). "Many studies have demonstrated an association between the expression of AhR/CYP1 genes and diabetes-related dysfunctions." (PMID 40408591, 2025). "The mean relative expression of AHR was lower in patients, suggesting the downregulation of AHR in patients with type 1 diabetes mellitus." (PMID 39211721, 2024). "Studies on the correlation between diabetes and AHR primarily examined the toxicological impact of exogenous substances like TCDD." (PMID 39575260, 2024). "AHR, in turn, is a cytoplasm-resident ligand-activated transcription factor with many functions in health and disease, including diabetes and liver diseases." (PMID 37305057, 2023). "The significance of three-way interaction of exercise, NLE, and diabetes means that the interaction among the two factors (exercise × NLE) is different across the levels of the third factor (diabetes) for AHR, CYP1A1, KYN, IDO1, and MDA." (PMID 37305057, 2023). "In our previous investigation, we found that AhR regulated the energy balance, insulin sensitivity, and glucose metabolism in the diabetes condition involved in the regulation of the VEGFβ- and TGFα pathway." (PMID 36232555, 2022). "Human exposure to the potent AHR agonist TCDD increases the risk of developing neuropathologies, cancers, cardiovascular disease, diabetes, and neurodevelopmental disorders." (PMID 36523606, 2022). "One of the current hot research topics is investigating the role of AhR activation by environmental pollutants on glucose homeostasis and insulin secretion, and hence the pathogenesis of diabetes mellitus." (PMID 36418969, 2022). "Both 3-IAA and 3-IPA have shown antioxidant and low pro-oxidative properties and immune regulation through the activation of the aryl hydrocarbon receptor, and 3-IPA has been inversely associated with diabetes and inflammation." (PMID 35684039, 2022). "As an example, administration of the AHR agonist TCDD prevented diabetes onset in NOD mice by increasing the frequency of Foxp3+T cells in pancreatic lymph nodes." (PMID 35757772, 2022). "Although the AhR pathway has been well investigated in the past decade for its potential role in various diseases, including cancer, diabetes, and cardiotoxicity, there is a major void when it comes to ASD." (PMID 34502168, 2021).
diabetes (continued). "HDAC inhibition by NaB has been reported to mitigate diabetes-provoked oxidative damage in aortic endothelial cells by triggering Nrf2 activation through improving aryl hydrocarbon receptor (AHR) and p300 occupancy at the Nrf2 promoter." (PMID 34071497, 2021). "In our current findings, we discovered that the AhR agonist VAF347 not only inhibited diabetes-mediated VEGF and retinal inflammation, but also systemically ablated hyperglycemic induced IL-6 production." (PMID 33919327, 2021). "Using the CALA and ATP assays, we previously demonstrated that serum AhR bioactivity is elevated but ATP levels are reduced in subjects with diabetes and impaired glucose tolerance." (PMID 28839207, 2017). "The AhR directly activates and transcriptionally regulates expression of IL-8, and IL-8 and TCDD were associated with diabetes in a cross-sectional analysis of data from an NHANES cohort." (PMID 26685285, 2016). "Understanding the mechanisms involved in AhR-induced diabetes has the potential to revolutionize our understanding of type 2 diabetes." (PMID 21849270, 2011). "The interaction of omeprazole with diabetes involves the activation of AhR." (PMID 41440753, 2025). "Therefore, this study aimed to evaluate the frequency of Tr1 cells and their association with aryl hydrocarbon receptor (AHR) and interferon regulatory factor-4 (IRF4) gene expression levels in type 1 diabetes mellitus (T1DM) compared to the healthy controls." (PMID 39211721, 2024). "Indoles potentially contribute to intestinal health and immune regulation through activation of the aryl hydrocarbon receptor (AhR) and the pregnane X receptor (PXR) as well as to an array of additional properties associated with diabetes mellitus or vascular regulation." (PMID 39472005, 2024). "In this review, we highlighted recent developments that point toward the role AhR may have on metabolism and, thus in the development of diabetes." (PMID 36418969, 2022). "Since age is a crucial factor in the development of diabetes, it has been suggested that age and BMI could be significant contributing factors to elevated AhR levels." (PMID 36418969, 2022). "AHR transcript (relative to that of GAPDH) turned out to be an independent risk factor of increased CRP levels [β Coefficient: 9.25(0.46–18.03), P = 0.040*], even after adjusting sex, age, disease status (diabetes duration and medications)." (PMID 32849564, 2020). "The objective of this report is to investigate the ability of participant serum-induced AhR bioactivity and mitochondrial dysfunction to predict the development of diabetes in participants of the Rio Grande do Sul center of ELSA-Brasil, a cohort study of Brazilian civil servants initiated in 2008." (PMID 33046063, 2020). "AHR transcript (relative to that of GAPDH) turned out to be the only independent risk factor of increased CRP levels [β Coefficient: 55.04(18.65–91.43), P = 0.005**], even after adjusting sex, age, disease status (diabetes duration, and medications)." (PMID 32849564, 2020). "Based on known effects of AhR, including a ~23% incidence of diabetes in AhR null mice, we speculate that the important ARNT-partner for glucose regulation in hepatocytes may be AhR." (PMID 29190746, 2017). "A link between TCDD and diabetes has also been hypothesized through interaction between the AhR and peroxisome proliferator–activated receptor (PPAR) γ–mediated signaling pathways." (PMID 23674506, 2013). "Moreover, increased AhR expression and activity mediated by other exogenous and endogenous ligands can exert multifaceted effects on the pathophysiology of metabolic abnormalities, including diabetes." (PMID 41440753, 2025). "However, the precise impact of AhR on β-cell function and its contribution to diabetes development or progression remains unclear." (PMID 39791758, 2025). "In type 2 diabetes mellitus (T2DM), AHR activation can interfere with insulin receptor signalling and amplify vascular inflammation." (PMID 40949107, 2025).